TNF (tumor necrosis factor)
Diseases named in the same sentence as TNF in open-access papers (continued):
Sharing a sentence is not in itself a finding about the gene and the disease.
infection (continued). "Macrophages and NK cells are critical innate cell effectors in Xenopus host response during early stages of FV3 infection, and increased expression of IL-1β, TNF-α, Mx1, and IFN-γ genes was detected in infected tissues and leukocytes of adult frogs." (PMID 34675918, 2021). "In the present study, the mRNA expression of inflammatory cytokines (IL-1β, IL-6, TNF-α) in the trachea and lung of group IV was lower compared with the expression levels of other groups from day 1 to 7 post-infection." (PMID 34988139, 2021). "Information from GP’s regarding antibiotic-treated infections was retrieved from 140 children who were exposed to anti-TNF-α in utero." (PMID 33046558, 2021). "We previously reported that LAD2 cells infected with A. baumannii with a multiplicity of infection (MOI) 50 released about 70 pg/mL TNF-α and 60 pg/mL IL-8, and both of these pro-inflammatory mediators in culture medium activated neutrophil transmigration." (PMID 33802578, 2021). "These outcomes were related to smaller numbers of IFN-γ and TNF-α T CD4 producing cells at the site of infection." (PMID 34745100, 2021). "C-reactive protein is a marker for infection, increases in response to systemic inflammation and is mainly synthesized by hepatocytes in response to proinflammatory cytokines (IL-1, IL-6, and TNF-α)." (PMID 33937367, 2021). "Amongst these, mRNA of the inflammatory cytokine TNF-α increased over time with a peak at 18 h from infection." (PMID 34357987, 2021). "We confirmed that TNF-mediated restriction of viral spread depends on cell death, supporting that viral spread depends on the interplay between infection and death." (PMID 34016976, 2021). "Compared with the normal control group, infection by ETEC K88 significantly increased serum TNF-α, IL-6, IL-1β, IFN-γ, VIP, sIgA and histamine levels, as well as the β-hexosaminidase, tryptase and MPO activities." (PMID 34899686, 2021). "One of the earliest sources of TNFα during infection, MCs can release pre-formed TNFα via degranulation immediately upon pathogen detection." (PMID 33680987, 2021). "TLR4 blockage on hMDMs resulted in an increase in the production of TNF-α upon infection of hMDMs with Sporothrix species." (PMID 34867977, 2021). "TNFα peaked in the BALF of both strains of mice at day 27 post-infection, however, this cytokine was observed at lower levels in the IL-4Rα−/− neonates." (PMID 34682248, 2021). "Anti-TNF-alpha treatment was associated with more than 3-fold risk of suffering from SARS-CoV-2 infection, although in all cases infection was mild." (PMID 35155485, 2021). "For example, CCL-2, -3 and -20 recruit monocytes, CCL-17 recruits dendritic cells (DCs), and IL-6, TNF-α and IL-23 attract T lymphocytes to the site of infection." (PMID 35095865, 2021). "TNF-α is mainly secreted by activated monocytes and macrophages, and it has regulatory cytokines involved in host anti-infection, anti-tumor immunity, and other physiological functions." (PMID 34369557, 2021). "In zebrafish infected with V. parahaemoglobin, TNF-α in their spleen increased significantly in a time-dependent manner, and reached a peak at the 12 h after infection and then declined." (PMID 34869718, 2021). "Cytokine ELISA results further confirmed that, at 48 h after infection, the secretion of IFNg and TNFα in T2KO and DKO BALF was significantly reduced as compared with WT and TKO mice." (PMID 34939151, 2021). "M protein from Th4M virus lacks the affinity for the NF-κB signaling protein RelAp43 and therefore allows the induction of IFN-β, TNF-α and other pro-inflammatory cytokines upon infection." (PMID 34970230, 2021). "Both infection with Lm and stimulation with TNF significantly increased numbers of p-MLKL+ cells and the amount of p-MLKL per cell in OTUB1-deficient HepG2 cells as compared to OTUB1-sufficient HepG2 cells." (PMID 33712742, 2021).
infection (continued). "The presence of an intrauterine infection induces the production of TNF-α in the amniotic fluid, and, therefore, TNF-α has been implicated in the pathogenesis of infection-associated preterm labor." (PMID 33800521, 2021). "As for pro-inflammatory cytokines and chemokines, we observed that the transcripts of CCL5 (RANTES) increased significantly after infection whereas moderate increases of IL-18, IP-10 and TNF-α transcripts were detected in UT-SCC-60A cells." (PMID 33481814, 2021). "The expression levels of the cytokines IL-6, IL-8 and TNF-α in the infected group were significantly higher than those in the control group at 12 h and 24 h post-infection." (PMID 34674760, 2021). "On the other hand, the IL-6 cytokine, which is associated with severity and death of VL, was related to the impairment of TNF-α secretion soon after infection and to the consequent inhibition of Th1 response." (PMID 34777391, 2021). "In turn, a dramatic rise in IL-1β, IL-6, and TNF-α plasma concentrations was evident 20 hours after infection in i.v. iron-treated Fth-KO animals as compared with control and iron-administered WT animals and control-treated FthΔ/Δ mice." (PMID 34236052, 2021). "Animals that had their treatment halted succumbed to infection in the same time period as mice still on anti-TNFα therapy." (PMID 35174101, 2021). "In acute inflammation, levels of TNF-α and other proinflammatory cytokines subside as infection is resolved." (PMID 34210153, 2021). "Typically, Th1 responses are characterized by changes in TNFα, INFγ, nitric oxide, IL-1 and IL-6, which are important in promoting and maintaining proinflammatory responses during infection." (PMID 34798906, 2021). "Both IL-1β and TNF-α can be secreted by macrophages in response to viral infections in the infection site." (PMID 34578465, 2021). "Consistently, Trim31−/− mice also had lower levels of IL-6 and TNF-α in the homogenates of kidney and liver after 5 days of infection with C. albicans." (PMID 34362877, 2021). "panamensis-infected C57BL/6 mice, which are unable to activate TLR-dependent pathways, present a decreased ability to secrete TNF and increased parasite burden at early times of infection." (PMID 34691019, 2021). "In response to the infection, the acute increase of different circulating pro‐inflammatory cytokines (including IL‐6, IL‐1, TNF‐ α, and interferon) is correlated directly with an unfavorable prognosis in COVID‐19." (PMID 33512742, 2021). "PA14 and PA14 fliC::tn in comparison to other transposon mutants also demonstrated extensive THP-1 cell death within 1 h of infection, which resulted in compromised production of TNF and IL-8 by both PA14 and PA14 fliC::tn." (PMID 33664232, 2021). "A large number of cytokines are produced in the process of infection, among which TNF-a plays a powerful immune regulatory role in host immune response." (PMID 34745113, 2021). "Mabs infection robustly increased the production of proinflammatory cytokines including TNF-α, IL-6, and IL-1β in BMDMs at 18 hpi." (PMID 34447358, 2021). "Human peripheral monocytes from L. braziliensis-infected patients with CL exhibited higher expression of TLR2, TLR4, TNF-α and IL-10 upon infection in vitro with L. braziliensis." (PMID 33924130, 2021). "TNF-α is a pyrogen cytokine released from immune cells in the acute phase of inflammation and infection." (PMID 34224085, 2021). "We observed increased levels of CXCL1, CCL2 and TNF-α in the spleens of Δisp2-infected mice after 4 days of infection." (PMID 34153047, 2021). "We found upregulation in expression of the proinflammatory cytokines IL-1β, IL-6, TNF-α, and IL-12p35 as well as the chemokine CXCLi1 in chMoDCs treated with S. Typhimurium during the early phase of infection (6 h)." (PMID 34446765, 2021).
infection (continued). "In our analysis, after infection diagnosis in susceptible dogs, PGE2 correlated with TNFα, IL-2, IL-15, and IL-7, most of them with pro-inflammatory functions, possibly attempting to decrease the inflammatory immune response." (PMID 33617528, 2021). "Despite aforesaid success, however, the current therapeutic paradigm of global TNF-α blockade has several limitations, including adverse effects (serious infection), low rates of disease remission and generation of anti-drug antibodies." (PMID 34627365, 2021). "In contrast, the expression of other inflammatory cytokines TNF, IL-6, and IL-8 was increased upon infection by chronic infection isolates compared to early isolates." (PMID 33664232, 2021). "TNF-α also regulates IL-8 production, a chemokine capable of recruiting neutrophils and immune cells to the infection site." (PMID 34573721, 2021). "Infection of human whole blood with any Candida species led to the release of IL-8 and proinflammatory cytokines (IL-1β, IL-6, TNF-α)." (PMID 33024045, 2020). "In response to TLR7 (imiquimod) stimulation, monocytes had a modest TNF response, which significantly increased at peak infection." (PMID 32566226, 2020). "In response to TLR1/2 (PamCys2) or TLR4 (LPS) stimulation, monocytes produced a strong TNF and moderate IL‐12 response, which increased at peak infection." (PMID 32566226, 2020). "Serum levels of pro-inflammatory cytokines were similar among the participants with different infection status (TNF-α; p = 0.290, IL-1β; p = 0.442, IL-6; p = 0.686, IFN-γ; p = 0.801, IL-8; p = 0.546, IL-12; p = 0.154)." (PMID 33317454, 2020). "In P. berghei ANKA infection, IFN-γ and/or TNF and T cell-intrinsic T-bet inhibit GC Tfh, GC B cell formation, and IgG production in response to infection." (PMID 32634740, 2020). "One female African elephant, representing two clinical cases (tusk injury and infection), had TNF-α concentrations considerably higher than all other individuals tested." (PMID 32992555, 2020). "We showed that TNF-α induced β-catenin and suppressed IκB expression in HUVECs, and these effects were both attenuated by infection with Ad-CAST." (PMID 32665543, 2020). "We validate the establishment of suspended microscale (4 μL) infection cultures that secrete increased levels of proinflammatory factors IL-6, VEGF, and TNFα upon infection and form 3D aggregates (granuloma model) encapsulating the mycobacteria." (PMID 32974300, 2020). "Macrophage activation as an initial response after the infection was likely to have increased TNF-α production and stimulate NK cells to produce IFN-γ." (PMID 32190083, 2020). "CD4+ T cells from C57BL/6 as well as from BALB/c mice express huge amounts of IFNγ and lower amounts of TNFα in the infection with R. typhi with a peak response around day 7 postinfection, which is similar to the CD8+ T cell response." (PMID 33091016, 2020). "Increased TNF-α at the beginning of the infection is likely to have inhibited parasite multiplication and provided immunity protection through plasmodium." (PMID 32190083, 2020). "After a diagnosis of TB or MAC disease is made, anti-TNF therapy is usually halted at least until anti-mycobacterial therapy has been initiated and the infection is under control." (PMID 33552087, 2020). "We also measured an increase of IL-1β levels secreted at 4 h of infection, and the same pattern was repeated for TNF-α." (PMID 33253325, 2020). "There was a significant increase in secretion of IL-12 and TNF-α upon infection of RAW264.7 and RAW-ΔTLR2 cells with Ms_Rv1954A compared to Ms_Vc." (PMID 33163415, 2020). "As mentioned, L. donovani-infected WSX-1−/− mice produce greater levels of IL-12, IFN-γ, and TNF-α during the early phase of infection in comparison to wild-type mice." (PMID 32849534, 2020). "The TNF signaling pathway and IL-17 signaling pathway were detected to be significantly up-regulated after the infection of Ich." (PMID 32295151, 2020).
infection (continued). "After infection of J774 cells with S. suis, a large number of TNF-α and IL-1β were produced, indicating that S. suis triggered a severe inflammatory response in cells." (PMID 33329477, 2020). "The infection resulted in an increase of TNF-α or IL-6 mRNA expression in the hippocampus and cortex of infected WT mice." (PMID 33121515, 2020). "Many immune cells in the blood secrete TNF-α and IL-6, especially during infection and inflammation, and monocytes and macrophages in the peripheral blood and tissues mainly secrete large amounts of TNF-α and IL-6." (PMID 32976531, 2020). "The changes of plasma IL-6 levels were similar as TNF-α changes, which increased after infection and were observed with a highest level after 24 h of infection, and then gradually decreased after treatment." (PMID 32221396, 2020). "TNF-α is released by different types of immune cells to mediate the events involved in inflammation and infection." (PMID 32103450, 2020). "For example, infection of C57BL/6 mice with lymphocytic choriomeningitis virus (LCMV) known to systemically induce TNFα and IFN-γ by NK cells, cytotoxic T lymphocytes, and Th1 cells leads to prominent FAT10 mRNA induction." (PMID 32586037, 2020). "When compared to the samples from the WNHPV, the expression levels of ILs-4, -5, -10, -12, and -13, IFN-γ, IFN-α2, MIP-1α and TNF-α were significantly elevated compared to samples from all the pre-acquisition and infection visits (all p < 0.001)." (PMID 33102255, 2020). "We evaluated the production of TNF-α, IL-6 and IL-10 at different times from viral adsorption to 6 h and 24 h post infection." (PMID 32316163, 2020). "Infection of epithelial cells by SARS viruses triggers the release of cytokines such as TNF-α and IL-617, which are key cytokines in IMIDs, where they are known to aggravate inflammation and tissue damage." (PMID 32709909, 2020). "We also found a direct correlation in both PTB in mice with ascending infection and significant relationship between UP presence and increased TNFα, IL-1β, CXCL-1 and CXCL-2 cytokine expression in foetal membranes, placenta and the myometrium." (PMID 31924800, 2020). "TNF-α, a cytokine that plays fundamental but distinct roles during infection, exhibited a similar level of expression on an average (255 ±144 mRNA molecules), but 90% of cells expressed more than 100 mRNA molecules (evident of reduced variability)." (PMID 32918862, 2020). "TNFα was also significantly upregulated upon super-infection compared to uninfected and bacteria single-infected cells but not to IV PR8-M single-infected cells." (PMID 33333815, 2020). "To determine if CFTR KO alters macrophage cytokine production, we measured production of 5 cytokines (IL-8, IL-1β, IL-6, IL-10, and TNF-α) at baseline and in response to infection with B. cenocepacia." (PMID 32973772, 2020). "Real time qPCR analysis of major pro‐inflammatory cytokines including IL‐1β, TNF‐α, and IL‐6 showed a less severe inflammatory response in the LL‐37‐Lung after infection." (PMID 31782624, 2020). "The pro-inflammatory cytokine TNFα is produced mostly by activated T cells and macrophages upon the recognition of the invading pathogen during an ongoing infection." (PMID 33182721, 2020). "This was shown in both T. brucei and T. congolense infections, using TNF knock-out mice as well as treatment with anti-TNF neutralizing antibodies." (PMID 32218784, 2020). "The most important adverse effect of using TNF-α inhibitors in AS patients is infection, and if the immune system is weak, TNF-α inhibitors can be a burden." (PMID 33021982, 2020). "Treatment with proteasome inhibitor significantly inhibited the release of IL-1, IL-6, TNFα, MIP-1β (i.e. CCL4), and KC (i.e. CXCL1) at their peak time-points in Balb/c mice after infection with the highly pathogenic avian H5N1 influenza A virus." (PMID 33362782, 2020).
infection (continued). "Animal studies have also shown increased levels of tumor necrosis factor-alpha (TNFα) and interferon-gamma (IFNγ) during infection." (PMID 33224678, 2020). "Both IL-6 and TNF-α can contribute to the elimination of Giardia, and IL-6 can modulate B cell maturation and induce antibody class switching to IgA during infection with Giardia." (PMID 32283818, 2020). "TNF, IL-1β, and IL-6 are important cytokines that mediate initial response of innate immune system to infections." (PMID 32133014, 2020). "In epithelial cells, HSV-1 can induce the secretion of TNFα, IL-1β and other inflammatory factors, that is, the inflammatory response participates in the host’s resistance to pathogen infection." (PMID 33195272, 2020). "It is well known that C. acnes induces the release of proinflammatory cytokines and chemokines, including IL-1β, IL-6, interferon (IFN)-γ, TNF-α, and IL-8 at the onset of infection." (PMID 32867396, 2020). "The levels of IL-1β, IL-6, and TNF-α were initially detected at 4 h after infection and gradually increased in a time-dependent manner." (PMID 32433516, 2020). "Along with IL-6 and the soluble IL-2 receptor, TNF-α levels increase early in the infection and remain elevated throughout the infection." (PMID 32961074, 2020). "NF-κB and TNF-α signaling pathways appeared to be mainly modulated upon infection, coordinating the expression of several effector proteins with proinflammatory and pro-fibrotic phenotypes." (PMID 32500038, 2020). "In a few hours following onset of infection, tumor necrosis factor alpha (TNF-α), IL-8, and monocyte chemoattractant protein-1 are secreted." (PMID 32629817, 2020). "In Mtb-infected hMDMs, however, DFX boosted secreted levels of IL1β and TNFα, exhibiting significant effects on IL1β at 0 and 3 h post infection, while displaying a significant effect on TNFα levels when added 24 h before infection." (PMID 32477344, 2020). "BTs increased from 35.0 °C–35.5 °C to 37.2 °C–39.0 °C, and the levels of plasma TNF-α and IL-6 increased after 24 h of infection in the three groups." (PMID 32221396, 2020). "It is established that increased mitochondrial Ca2+ is a primary modulator for the production of cardiomyocyte tumor necrosis factor (TNF)-α, interleukin (IL)-1β and IL-6, leading to cardiac inflammation or dysfunction upon injury or infection." (PMID 32327997, 2020). "All investigated cell types, encompassing macrophages as well as CD4+ and CD8+ T cells, were found to produce TNF-α 8 days post-infection." (PMID 32069329, 2020). "After ME-49 strain infection, we observed changes in TNF-α serum levels observed with an ELISA spectrophotometer." (PMID 32802484, 2020). "Among the three epitope-based vaccine groups, the IL-4 levels of Amastin-Gp63 group were the lowest, and the TNF-α levels of that were the highest at 4th and 8th week post-infection." (PMID 32176727, 2020). "M1 macrophages triggered by TNF-α or LPS are proinflammatory, playing central roles in host defense against pathogen infection." (PMID 33101281, 2020). "On the contrary, IL-6 and TNFα were more expressed in infected supernatants, increasing concentration over the 3-day infection period." (PMID 32455939, 2020). "In TB, IL-17A contributes indirectly to granuloma formation and the recruitment of IFNγ/TNF/IL-2-producing multifunctional T cells to the site of infection by the induction of various chemokines." (PMID 33334075, 2020). "We determined the expression levels of mRNA encoding the three pro-inflammatory cytokines IL-6, IL-8, and TNFα to help understand the impact that 6K-F17 treatment has on infection-mediated inflammation." (PMID 32092967, 2020). "Ex vivo, BAL CD2+ γδ T cells, without H1N1pdm09 stimulation, secreted IFNγ and TNF early post infection with the highest frequency of 0.6% IFNγ and 1.6% TNF at 3 DPI." (PMID 33603740, 2020).